GAS6 (growth arrest specific 6)
Diseases named in the same sentence as GAS6 in open-access papers (continued):
Sharing a sentence is not in itself a finding about the gene and the disease.
cancer (continued). "Targeting Gas6 or TAM receptors has emerged as a potential therapeutic strategy in cancer treatment; indeed, inhibiting the Gas6/TAM axis could potentially disrupt the pro-tumorigenic signaling pathways and enhance the effectiveness of anticancer therapies." (PMID 39057085, 2024). "GAS6/Axl signaling functions as an important pathway governing cancer cell survival, proliferation, migration, and invasion, making Axl a marker of cancer progression and metastasis, and a potential target in cancer therapy." (PMID 38664641, 2024). "Despite this canonical pathway, cancer cells often bypass GAS6 dependence." (PMID 38474160, 2024). "Gas6 can promote cancer metastasis by upregulating Slug and inhibiting E-cadherin expression." (PMID 39451556, 2024). "Moreover, GAS6 (growth arrest–specific 6), the ligand of the AXL receptor tyrosine kinase family is associated with immune regulation and cancer development." (PMID 39568788, 2024). "In addition, GAS6 overexpression was shown to predict poor prognosis of cancer patients in the clinic." (PMID 38033034, 2023). "Currently, many reports have suggested Gas6 plays an important role in cancer." (PMID 37265798, 2023). "Published clinical studies of GAS6/AXL related drugs for cancer." (PMID 37265798, 2023). "One of the mechanisms for AXL to help DTCs survival is proposed that AXL could bind to the ligand GAS6, while the activation of the GAS6/AXL axis can promote the dormancy of cancer cells." (PMID 37638338, 2023). "It is thus plausible that rapid uptake of AXL and its subsequent recycling and delivery to nascent focal adhesions might play an important role during GAS6–AXL-induced cancer-cell migration and invasion." (PMID 35622156, 2022). "The majority of the internalized AXL is not degraded but recycled to specifically sustain the downstream activation of AKT at the plasma membrane, that may promote GAS6–AXL-induced cancer-cell migration and invasion." (PMID 35622156, 2022). "The role of Gas6 can vary in different cancer types and depends on the gene regulation." (PMID 35760058, 2022). "Moreover, hMENA/hMENAΔv6 isoforms were also shown to regulate AXL levels in cancer cells, whereas their silencing inhibited GAS6-induced AXL expression and AKT phosphorylation." (PMID 36422541, 2022). "Next, we tested whether Gas6 is sufficient to promote the regrowth of gemcitabine treated cancer cells." (PMID 35022267, 2022). "The role of Gas6 and Axl in cancer has been reviewed previously." (PMID 34576116, 2021). "The effect of fully carboxylated Gas6 on various types of cancer?" (PMID 34836355, 2021). "Examples of cancer related genes in the network included GAS6, MAP3K4, PRKD1, PTPRD, and VEGFA." (PMID 34434222, 2021). "Similarly, analysis of TCGA data showed that patients with luminal B, Her2+, and basal-like (which includes TNBC) tumors expressed significantly lower levels of Gas6 mRNA, relative to normal-like cancers." (PMID 32352034, 2020). "In particular, GAS6 promotes the transition of cancer cells into DCCs in the bone marrow." (PMID 32300189, 2020). "In HER2+ cancers at least, GAS6 appears to be dispensable for metastasis." (PMID 32148495, 2020). "Importantly, the addition of recombinant GAS6 (rGAS6) to hMENA(t) silenced CAFs rescued cancer cell invasiveness in PANC‐1." (PMID 32909687, 2020). "Macrophage-derived GAS6 is a critical regulator of the transition from premalignant to invasive cancer and could be a biomarker of progression for patients with early-stage cancer." (PMID 32148495, 2020). "Our findings suggest that the activation status of NK cells should also be assessed in cancer patients and could be used as a biomarker to monitor response to anti-Gas6/Axl therapies." (PMID 32174917, 2020).
cancer (continued). "To investigate the role of hMENA in ligand‐dependent AXL signaling, we treated PANC‐1 cells with rGAS6 and we found that hMENA silencing inhibits GAS6‐mediated AXL and AKT phosphorylation and reduced cancer cell invasion toward GAS6 as detected by Matrigel transwell invasion assay." (PMID 32909687, 2020). "In support, numerous studies have shown Gas6-independent activation of Axl in cancer." (PMID 32352034, 2020). "Hence, further studies are warranted to understand the role of the Gas6/Axl signaling in the cancer immunity cycle." (PMID 32660000, 2020). "We demonstrate that GAS6-induced pAKT is a possible PD marker for the inhibition of MER kinase in G361 cells, and developed a cell-based functional assay for screening small-molecule inhibitors of MER kinase for potential therapeutic utility in treating GAS6/MER-deregulated human cancers." (PMID 32042425, 2020). "Gas6 is frequently expressed in cancers and its levels correlate with poor prognosis." (PMID 32355198, 2020). "Higher levels of Gas6 correlate with increased mortality of cancer patients." (PMID 31903163, 2019). "GAS6 could promote cellular survival and down-regulate apoptotic factors, induce cell proliferation, and enhance the migration of cancer cells." (PMID 31028135, 2019). "The expression of Gas6 is widespread in many tissues and cells, including immune cells, endothelial cells, vascular smooth muscle cells, bone marrow cells, adipocytes, platelets and various cancer cells." (PMID 31316104, 2019). "Gas6 plays a significant role in the development of numerous cancer types." (PMID 29386018, 2018). "Gas6/TAM have a significant role in the survival of cancer cells." (PMID 29386018, 2018). "Finally, we introduce recent studies on Gas6/TAM targeting in cancer therapy, which will assist in the experimental design of future analyses and increase the potential use of Gas6 as a therapeutic target for cancer." (PMID 29386018, 2018). "Furthermore, other laboratories have shown that cancer cells can direct stromal cells, including osteoblasts, to increase autocrine Gas6/Axl signaling leading to increased cancer cell growth and survival in bone." (PMID 29867053, 2018). "Above, we describe cell autonomous roles of Gas6/TAM in cancer cells." (PMID 29386018, 2018). "Recently, the role of Gas6 in various cancers has become clearer." (PMID 28333143, 2017). "The endogenous expression of GAS6 contributes to maintenance of cancer stem cells." (PMID 28286742, 2017). "Numerous studies regarding cancer therapy have targeted Gas6 and TAM receptors with good results." (PMID 28333143, 2017). "This review presents the significant roles of Gas6 in cancers from different systems and may contribute to the continued promotion of Gas6 as a therapeutic target." (PMID 28333143, 2017). "Can warfarin or non-γ-carboxylated Gas6 proteins be considered as adjuvant cancer therapeutics?" (PMID 27916840, 2016). "A high Gas6 level may predict nodal metastases, late cancer stage and reflect poor prognosis in OSCC patients." (PMID 26207647, 2015). "In a survey of cancer-associated receptors and ligands in primary PDA cells in culture, we noted that the receptor tyrosine kinase Axl was highly expressed, with modest expression of its endogenous ligand Gas6." (PMID 26438693, 2015). "Elevated Gas6 level was also predictive for nodal metastases and late cancer stages, and could reflect poor prognosis for OSCC patients." (PMID 26207647, 2015). "Under these conditions, inactivation of Gas6 may decrease the invasion/migration ability of OSCC cells and Gas6 could increase proliferation and survival of cancer cells." (PMID 26207647, 2015). "Notably, application of sAxl to target Gas6/Axl signaling has been proposed as a therapeutic strategy in cancer." (PMID 25344858, 2014). "There is also evidence in other cancer types that GAS6 may be involved in resistance to chemotherapy." (PMID 23878800, 2013).
cancer (continued). "Consequently blocking the Gas6/AXL signaling pathway represents an attractive therapeutic strategy in cancer." (PMID 23077658, 2012). "When the Gas6 mRNA results were examined in relation to the PRB immunohistochemical profiles, there was a positive association between PRB immunohistochemistry (positive>10%) and Gas6 mRNA levels in curatively resected cancers (stage 4 disease was omitted)." (PMID 18283315, 2008). "Since GAS6/AXL interaction has been described to trigger various signaling pathways in cancer cells, including PI3K-AKT, NFκB, RAS-MEK-ERK, SRC-FAK and JAK-STAT 8; it might be interesting to further elucidate the downstream mechanisms of action of sdAb20-Fc in AML." (PMID 38773967, 2024). "Except for BAI1, CD31, and MerTK, the enhanced expression of Axl, Tyro3, Gas6, MFGE8, Stab2, Tim-4, CX3CL1, IDO1, Rac1, and PD-L1 was associated with decreased sensitivity to many drugs, which may partially explain the resistance to chemotherapy in cancers." (PMID 36059952, 2022). "The Gas6/ProS1–TAM interaction is involved in a number of cellular biological processes including regulating the immune system and inflammation, cell survival, migration, proliferation and removal of apoptotic cells, and aberrant TAM signalling has also been implicated in cancers." (PMID 35518197, 2022). "We focused not only on MER expression level in various human cancer cell lines but also on whether their GAS6-induced AKT phosphorylation was dependent on MER receptor status; this was a key factor that led to identifying G361 cells as a suitable cell line for the endogenous MER cellular assay." (PMID 32042425, 2020). "In addition to VEGF, PDGF-B and PlGF, Gas6 is also highly upregulated in cancer cells." (PMID 32499572, 2020). "Notably, cancer therapy-induced cellular apoptosis will lead to accumulation of cellular apoptotic materials including PtdSer, Gas6, and ProteinS, which may contribute to survival advantages essential for therapy resistance." (PMID 30944303, 2019). "Indeed, activation of AXL by GAS6 was demonstrated in various cancer models." (PMID 28118606, 2017). "As such, generalized antagonists that act as pan-TAM inhibitors and target the extracellular binding site between Gas6 and TAMs may have opportunistic pleiotropic paracrine effects for multiple effector cells that coordinately improve outcomes in cancer patients." (PMID 28272423, 2017). "Similarly, it is also possible that non-γ-carboxylated Gas6 proteins, to possibly developed as cancer therapeutics, might act as ligand traps to bind and prevent subsequent TAM activation." (PMID 29176978, 2017). "It prevents direct AXL/AXL or GAS6/GAS6 interactions, influencing processes such as epithelial-to-mesenchymal transition (EMT), a key event in cancer progression." (PMID 39924521, 2025). "The Gas6/TAM system has been widely studied in different human conditions, with a particular focus on cancer." (PMID 39057085, 2024). "There were strong connections via the GAS6-AXL/MERTK and THBS1-CD36/CD47/ITGA4/ITGB1/LRP1 axes between cancer cells (contributing ligands) and TAMs (contributing receptors)." (PMID 38169544, 2024). "When it interacts with its specific ligand, GAS6, the AXL receptor influences a range of cell signaling pathways and the interaction among different elements of the tumor environment, such as cancer cells, endothelial cells, and cells of the immune system." (PMID 38474160, 2024). "It was demonstrated that GAS6, which can bind to all three TAM receptors, is secreted by bone marrow stromal cells, especially osteoblasts, and induces dormancy in several cancer entities via AXL." (PMID 38203403, 2023). "This prevents m6A from being able to suppress GAS6-mediated effects, thereby promoting the transcription of EMT-related genes and inducing cancer progression." (PMID 38137547, 2023).
cancer (continued). "In contrast, the expression levels of TXNDC5, CD38, GAS6, FKBP2 and SDC1 were increased in the late stage of LUAD progression, indicating potential distinct roles in the occurrence and progression of the cancer." (PMID 37728413, 2023). "GAS6–AXL signaling is crucial for cancer progression and metastasis in several types of cancers AXL can be activated in both GAS6–dependent and –independent manners." (PMID 37834326, 2023). "In line with this, our prior study demonstrated that activation of GAS6–AXL signaling enhanced spreading and invasion of cancer cells, and macropinocytosis contributed to these processes." (PMID 35622156, 2022). "Many laboratory studies have shown that the GAS6/AXL axis promotes cell invasion, proliferation and survival, thus contributing to cancer progression and metastasis." (PMID 35158733, 2022). "Gas6/TAM binding then triggers receptor activation and numerous downstream signaling pathways on both cancer and host cells." (PMID 35127700, 2021). "Cancer-derived Hh also promoted the expression of growth factors such as IGF1 and GAS6 by fibroblasts, which reflected back on cancer cells." (PMID 34356110, 2021). "The PtdSer, which is exposed on the apoptotic cancer cells, binds to PROS and Gas6 and transmits an “eat me” signal to the macrophages, which express abundant MERTK." (PMID 33562150, 2021). "AXL and its ligand, i.e., growth arrest-specific 6 (GAS6) proteins, are expressed on many cancer cells, and the GAS6/AXL pathway is reported to promote cancer cell proliferation, survival, migration, invasion, angiogenesis, and immune evasion." (PMID 34778071, 2021). "To identify the potential downstream component of the GAS6/MER pathway, we compared the expression of MER, AXL, and TYRO3 among various human cancer cell lines including HeLa, DU145, THP-1, RKO, SKM1, A549, OCI-LY3, G361, and HL60." (PMID 32042425, 2020). "It would be interesting to determine the co-occurrence of Gas6 elevation and PIK3R2 amplification, as well as the corresponding AXL activation status in cancer patients." (PMID 32385243, 2020). "In this study, we conducted cell migration and invasion assays under serum-free conditions, using GAS6 or HGF as chemoattractants to dissect the roles of AXL and MET in cabozantinib-mediated inhibition of cancer cell migration and invasion." (PMID 32055714, 2020). "Gas6 bridges between PS and TAM receptors, thereby promoting cancer cell proliferation and migration." (PMID 32370748, 2020). "In the present study, we have demonstrated that Gal-3 is a novel functional agonist for Tyro3 RTK in human cancer cells and have compared it directly against both well-established TAM ligands Gas6 and ProS1." (PMID 32664510, 2020). "This review will focus on PtdSer as a cofactor required for stimulating TYRO3, AXL and MERTK – comprising the TAM family of receptor tyrosine kinases by their ligands Protein S (PROS1) and growth-arrest-specific 6 (GAS6) in inflammation and cancer." (PMID 31775787, 2019). "With respect to the steps of EMT, which are essential for metastasis, the researchers of the present study studied a number of genes reported to have a role in EMT in different cancers, such as Claudin-1, Cofilin-1, AXL, and GAS6." (PMID 31700829, 2019). "Under these conditions, both ProS1 and Gas6 significantly protected cells from apoptosis in both SCC-25 (Tyro3 and Axl) and MGH-U3 (Tyro3 only) cancer cell lines." (PMID 31766614, 2019). "Therefore, targeting Gas6 may effectively aid existing cancer treatments." (PMID 29386018, 2018). "The AXL ligand, GAS6, had the third highest expression in MPM, versus the other cancer datasets, with a mean log2 value of 13.06." (PMID 29375377, 2017). "Next, we describe and discuss the involvement of Gas6 and TAM receptors in cancers from different organ systems." (PMID 28333143, 2017).
cancer (continued). "Most importantly, this work has led to the development of a variety of GAS6/AXL inhibitors that have been tested in preclinical and clinical studies and are promising new therapeutic strategies for cancer therapy." (PMID 27834845, 2016). "Axl and Gas6 are highly expressed in many human primary PDA tumors (TCGA data), containing both cancer and stromal cells." (PMID 26438693, 2015). "The sequence and nature of the antiapoptotic and angiogenesis events resulting from Gas6/Axl interactions have been most extensively studied in murine NIH-3 T3 fibroblasts and many different types of cancer." (PMID 24572151, 2014). "In cancer cells, where the expression levels of RTKs are high, ED shedding manifests a switch from the canonical to non-canonical GAS6- and PROS1-independent pathways via the dimerization of either full-size or truncated TAM receptors with other RTKs." (PMID 40044635, 2025). "To test whether GAS6-CAR-T cells can also kill CSCs, we produced cancer cell line-derived CSCs as sphere cultures from PANC1 and MIA PaCa2 cells." (PMID 37475048, 2023). "Finally, TNFSF10—TNFRSF10B (TRIAL—TRIAL-R), SIRPA—CD47 (“don't eat me”), C5AR1—RPS19, and GAS6—AXL act as negative regulators of the innate immune system by inhibiting cytokine responses, phagocytosis of cancer cells, and promoting the immunosuppressive TME." (PMID 37823774, 2023). "Mechanistically, we found that cessation of chemotherapy induces the infiltration of neutrophils and that neutrophils activate AXL receptor on metastatic cancer cells, via secretion of the AXL receptor ligand Gas6, leading to cancer cell growth at the metastatic liver." (PMID 35022267, 2022). "GAS6 expression in CAFs maintains the protumoral GAS6/AXL paracrine axis and has been described as serving a vital role in the EMT, drug resistance, and metastasis of multiple types of cancer." (PMID 36422541, 2022). "GAS6 and GAS6-AS1 are both involved in the pathogenesis of cancers." (PMID 35962353, 2022). "We pretreated human Panc1 cells and mouse derived KPC cells with gemcitabine and measured regrowth of the cancer cells in the presence or absence of recombinant Gas6." (PMID 35022267, 2022). "Importantly, we and others revealed that GAS6–AXL-induced macropinocytic uptake of albumin and cell debris improves the survival of cancer cells under nutrient-deprived conditions." (PMID 35622156, 2022). "Increased plasma Gas6 and possible negative effects in critically ill and cancer patients is a new research area, highlighting a possible risk with vitamin K1 treatment." (PMID 34836355, 2021). "•GAS6-AXL and HGF-MET pathways independently contribute to cancer cell migration." (PMID 32055714, 2020). "In line with the oncogenic role of these genes, we observed a decrease in proliferation of H226 cells when either PDGFRB or COL1A1 were inhibited, additive to the effect achieved with GAS6 downregulation alone, supporting the existence of a SWINGN-dependent oncogenic hub in this cancer type." (PMID 32071317, 2020). "•Cabozantinib inhibits GAS6 and HGF combination-induced cancer cell migration." (PMID 32055714, 2020). "Similarly, in bone marrow, GAS6 from osteoblasts activates TAM family receptors on prostate cancer cells and switches on dormancy in proliferative cancer cells." (PMID 32300189, 2020). "•Cabozantinib inhibits GAS6 and HGF combination-induced cancer cell invasion." (PMID 32055714, 2020). "Moreover, AXL acts as a crucial regulator of cancer-related EMT; particularly in HCC, the cooperation between Gas6/Axl and TGF-β signaling pathways appears to be crucial in differentiation, EMT, and the advancement of invasion." (PMID 32517019, 2020). "In summary, our data show that the GAS6-AXL and HGF-MET signaling axes play a critical role in cancer cell migration and invasion, demonstrating that simultaneous inhibition of these pathways contributes to the anti-cancer effects of cabozantinib." (PMID 32055714, 2020).